CXCR4 (C-X-C motif chemokine receptor 4)
Diseases named in the same sentence as CXCR4 in open-access papers (continued):
Sharing a sentence is not in itself a finding about the gene and the disease.
glioblastoma (198 papers, 2006 to 2026). The most malignant astrocytic tumor (WHO grade IV). "Several studies have demonstrated that CXCR4 expression in glioblastoma is associated with a poorer prognosis and more infiltrative phenotypes." (PMID 36140541, 2022). "For example in patients with glioblastoma, a potential target is the overexpressed chemokine receptor-4 (CXCR4) which is associated with a poor clinical outcome." (PMID 32213992, 2020). "Visualization of CXCR4 expression using diagnostic PET with CXCR4-directed [68Ga]Pentixafor® has been demonstrated in glioblastoma patients." (PMID 32213992, 2020). "Multiple studies have shown that CXCR4 is overexpressed in glioblastoma cells, which is associated with increased invasive behavior of glioblastoma cells towards high SDF-1α concentrations." (PMID 32079173, 2020). "There is evidence that HIF1α directly induces VEGF and CXCR4 transcription by binding to hypoxia response element regions, while VEGF has also been implicated in CXCR4 upregulation of angiogenic vessels in glioblastoma." (PMID 29098360, 2018). "The results suggest that CXCL12/CXCR4 is involved in the progress of glioblastoma, regulating the expression of the molecules associated with stem-cell properties." (PMID 23961808, 2013). "Upregulation of CXCR4 expression has also been seen in glioblastoma-associated T cells, but whether glioblastoma employ a similar mechanism to affect T cell infiltration remains unknown." (PMID 37790751, 2023). "As indicated, the mechanism underlying the GNG4-silencing driven promotion of glioblastoma may be the inhibition of SDF1α/CXCR4 signaling." (PMID 34016944, 2021). "Plerixafor (AMD3100), a small molecule antagonist of CXCR4, has been widely studied in hematologic malignancies and is now being repurposed for glioblastoma." (PMID 40867316, 2025). "USL311 is another selective CXCR4 antagonist that is currently undergoing a clinical trial in glioblastoma (NCT02765165)." (PMID 38612911, 2024). "Glioblastoma-derived CXCL12 forms an autocrine-positive feedback loop through the tumor-bound CXCR4 in response to environmental stress." (PMID 38898023, 2024). "This was contrary to our expectation that the bone marrow of the older cohort of patients with glioblastoma would be populated by aged hematopoietic cells with a reduced regenerative potential and consequently lower CXCR4 levels." (PMID 39085419, 2024). "Of note, the authors found that CXCR4 is more highly expressed in glioblastoma CSCs than differentiated cancer cells, and the stem cells are more sensitive to PRX177561 compared to differentiated cells." (PMID 38612911, 2024). "In a preclinical model of glioblastoma, it was shown that the application of antiangiogenic drugs promoted an increase in the expression of CXCR4 (CXCL12 receptor) in tumor cells." (PMID 38255995, 2024). "AMD3100 was found to restrain glioblastoma vasculogenesis, specifically blocking the migration of bone marrow-derived cells to the primary tumor site and inhibiting the CXCR4/SDF-1 axis." (PMID 36980182, 2023). "Similar results were obtained by Kaplan–Meier analysis, t-ROC, and DCA assessment of IDH1-WT glioblastoma based on CXCR4 in PRSM." (PMID 37626511, 2023). "In in vitro experiments, we found that CXCR4 was significantly overexpressed in glioblastoma and was closely related to the inflammatory response of U251/U87 cells." (PMID 37626511, 2023). "CXCR4 is an excellent independent prognostic factor for glioblastoma and positively correlates with tumor inflammation." (PMID 37626511, 2023). "CXCR members have a significant impact on immune infiltration and survival prognosis of glioblastoma, with CXCR4 as an independent prognostic factor positively correlated with inflammation in glioblastoma." (PMID 37626511, 2023). "CXCR4 staining in the remaining 331 cores (78%) was highly variable, also within individual glioblastoma patients." (PMID 33550492, 2022).
glioblastoma (continued). "CXCR4 is overexpressed in various cancers, including glioblastoma, and usually correlates with a poor prognosis." (PMID 36311790, 2022). "Within glioblastoma-infiltrating T cells, a large proportion of cells were positive for CXCR4 and the proportion of cells positive for chemokine receptors CCR4, CCR5, CCR6, CCR7, CXCR3, and CXCR6 ranged between 5-25%." (PMID 35464424, 2022). "EGF or HRG have been reported to promote CXCR4 serine and/or tyrosine phosphorylation in glioblastoma or BC cells leading to CXCL12-independent receptor activation of downstream cascades." (PMID 36233192, 2022). "In their study, variable CXCR4 expression was demonstrated in 38% of the cores in glioblastoma cells, and CXCR4 expression was high in only a subset of glioblastomas." (PMID 36140541, 2022). "We demonstrated that the polyphemusin II-derived peptidomimetic POL3026 and its PEGylated analog have suitable pharmacokinetics for non-invasive detection of CXCR4 expression in a U87-stb-CXCR4 glioblastoma mouse model." (PMID 35336029, 2022). "Using immunohistochemistry, high CXCR4 expression was found in a subset of glioblastomas as well as a large inter- and intra-tumor variation." (PMID 33550492, 2022). "Intriguingly, targeting CXCR4, a crucial molecule for brain microvasculature invasion by glioblastoma cells, suppresses tumor invasion and renders tumors sensitive to radiation therapy, thus presenting another potential intriguing target." (PMID 36119528, 2022). "A CXCR4 inhibitor (Plerixafor) combined with concurrent chemoradiation improved the local control of tumour recurrence in glioblastoma patients." (PMID 35468838, 2022). "One glioblastoma core in our ex vivo data showed CXCR4 staining of neurons, and the same was seen in a small subset of neurons in tumor-infiltrated cortex of one of the clinical patients." (PMID 33550492, 2022). "The expression of CXCR4 and CXCL12 mRNAs in glioblastoma increases with tumour grade and is associated with regions of necrosis and angiogenesis." (PMID 36140541, 2022). "Strikingly, there was a significant increase in the abundance of CXCR4 on all CD4+ T-cell subsets in glioblastoma compared to blood samples." (PMID 35464424, 2022). "At present, some clinical studies suggest that bevacizumab can improve vascular symbiosis induced by SDF-1α/CXCR4 in patients with glioblastoma." (PMID 35545781, 2022). "Here, we observed high proportions of both patient blood and glioblastoma T-cell subsets expressing CXCR4, and significantly greater abundance of CXCR4, by measure of gMFI, on glioblastoma T-cell subsets." (PMID 35464424, 2022). "We aimed to investigate the expression of CXCR4 in glioblastoma tissue to further examine the potential of these PET agents." (PMID 33550492, 2022). "In contrast, the stem bark ethanol and DMSO extracts of A. coriaria harvested in central Uganda had high cytotoxicity against the human glioblastoma cell line (U87.CD4.CXCR4) with CC50 of 6.4 and <4 μg/mL, respectively." (PMID 35103066, 2022). "Glioblastomas showed a large variation in CXCR4 mRNA expression and, however, were also the highest compared with lower grades." (PMID 33550492, 2022). "In conclusion, although CXCR4 mRNA expression appears to be highest in glioblastomas, glioblastoma tissue itself shows a large variation of CXCR4 expression, both within and between tumors." (PMID 33550492, 2022). "Taking into account the variable expression of CXCR4 in glioblastoma cells, it seems CXCR4 expression is high in only a subset of glioblastomas." (PMID 33550492, 2022). "AMD3100 has been showed to delay CXCR4-mediated metastasis and invasion of ovarian cancer and reduce self-renewal and survival in human glioblastoma stem-like cells." (PMID 35145271, 2022). "According to many studies of glioblastomas and neuroblastomas, CXCR4+ monocytes attracted to tumors induce the formation of new blood vessels within the tumors." (PMID 35269652, 2022).
glioblastoma (continued). "High expression of MIF and CXCR4 in glioblastoma cells under hypoxia conditions is reported to promote EMT of glioblastoma cells via a MIF-CXCR4-AKT pathway." (PMID 35842634, 2022). "Retrospective studies showed that the persistant CXCR4/CXCL12 expression after CRT is associated with tumor aggressiveness and poor prognosis in LARC, esophageal cancer, cervical cancer and glioblastoma 32, 53-55." (PMID 34976180, 2022). "MIF also promotes vasculogenic mimicry (VM) formation through the CXCR4-Akt-EMT pathway in glioblastoma to support malignant tumor progression." (PMID 35842634, 2022). "Our research opens a new line of study that allows us to deepen the relationship between NANOG and CXCR4 in glioblastoma cells." (PMID 34638956, 2021). "Several clinical trials are currently evaluating the clinical benefit of CXCR4 antagonists in glioblastoma patients." (PMID 34575965, 2021). "To find out if h-NANOG can regulate CXCR4 expression in human cancer cells, we studied how changes in h-NANOG level affected the expression of CXCR4 in human glioblastoma and astrocytoma cell lines." (PMID 34638956, 2021). "In VEGFR-expressing glioblastoma, it has been confirmed that VEGFR inhibitors upregulated CXCR4 through TGF-β/TGF-β receptor, and the inhibition of CXCR4 enhanced the efficacy of sunitinib (a multitarget TKI) in preclinical models of human glioblastoma." (PMID 33921219, 2021). "On the other hand, CXCR4 controls the migration of neuronal cells, and it is the most common chemokine receptor expressed by many cancer cells, including glioblastoma, where CXCR4 plays a role in cancer cell migration." (PMID 34638956, 2021). "Cxcr4 signalling has been shown to promote progression of many cancers in mammals including glioblastoma, through both cancer cell autonomous signalling and leukocyte interactions." (PMID 32325966, 2020). "miR-429 regulates the major number of pathways: "HIF1 signaling", "Acute Phase Response signaling", "Glioblastoma Multiforme signaling", "P2Y Purigenic Receptor signaling", "CXCR4 signaling " and “Growth hormone signaling”." (PMID 31903105, 2020). "Under hypoxic conditions, hypoxia-inducible factor 1 (HIF-1) and VEGF increase the expression of CXCR4 in human brain microvascular endothelial cells, which promotes glioblastoma angiogenesis." (PMID 33363463, 2020). "CXCR4 is a cell surface transmembrane G protein receptor; it is one of several “chemokine” receptors expressed on malignant tumors (including glioblastoma-GBM and primary CNS lymphoma-PCNSL) and on hematopoietic stem cells." (PMID 32239371, 2020). "This demonstrates that macrophages/microglia have a potent trophic role during glioblastoma initiation and Cxcr4 is required for their recruitment." (PMID 32325966, 2020). "Current phase I/II study showed that CXCR4 inhibitor Plerixafor was well tolerated as an adjunct to chemoirradiation in newly diagnosed glioblastoma patients and reduced tumor local recurrences by inhibiting postirradiation tumor revascularization." (PMID 33414786, 2020). "Through the further functional enrichment analysis of dysmethylated genes, such as CXCR4, TBX18, SP5, and TMEM22, several potential pathogenic functions are found to participate in the initiation and progression of glioblastoma." (PMID 33329750, 2020). "miR-190 regulates "P2Y Purigenic Receptor signaling", "Axonal Guidance signaling", "CXCR4 signaling" and "Glioblastoma Multiforme signaling"." (PMID 31903105, 2020). "SDF-1 was secreted by glioblastoma cells and served as a chemoattractant for EPCs that expressed the receptor CXCR4." (PMID 33036204, 2020). "We found that EZH2 epigenetically silenced miR-9, which directly targets the oncogenic signaling of CXCR4 in glioblastoma cell lines." (PMID 32635336, 2020).
glioblastoma (continued). "This approach is currently being tested in a Phase 1/2 study in adult patients with newly diagnosed glioblastoma assessing the impact of CXCR4 blockade with plerixafor combined with radiotherapy and temozolomide (NCT01977677)." (PMID 30813533, 2019). "By using in vitro and in vivo approaches, they have demonstrated that the expression of CXCR4 improve the migration to U87-MG glioblastoma cells resulting in a stronger anti-tumor effect compared with control groups." (PMID 30939820, 2019). "Then, we retrieved data (NCBI GEO dataset: GSE23806) on the expression of Notch1 signaling molecular and CXCR4 in 36 conventional cell lines, 27 glioma stem like cell lines and 17 glioblastoma derived neurospheres." (PMID 31382985, 2019). "In oral squamous cell carcinoma and glioblastoma, vascular endothelial growth factor has been shown to upregulate CXCR4 expression." (PMID 30642351, 2019). "On the other hand, NK cells engineered to co-express a chimeric antigen receptor (CAR) and the chemokine receptor CXCR4 enhanced NK cell infiltration and tumor cell killing in a glioblastoma tumor model." (PMID 30319622, 2018). "MiR-663 was also shown to decrease glioblastoma by targeting transcripts encoding CXCR4, the receptor of chemokine CXCL12 that is known to be involved in glioblastoma progression, and miR-663 overexpression prolonged survival of mice with glioblastoma." (PMID 29987196, 2018). "When tissue samples were evaluated, poor correlations were reported for glioblastoma and small cell lung cancer between 68Ga-pentixafor SUVs and CXCR4 immunoreactivity." (PMID 29088715, 2017). "68Ga–Pentixafor-PET-CT was chosen as the imaging agent because of its strong affinity for CXCR4, which is reportedly overexpressed in glioblastoma lesions." (PMID 28157157, 2017). "In the context of glioma, CXCL12/CXCL12-receptor (CXCR4/CXCR7) autoregulatory signaling has been demonstrated to be important for glioblastoma survival and angiogenesis, while CX3CL1/CX3CR1 axis signaling in glioma cells controls glioma cell invasion." (PMID 28380429, 2017). "Similar findings were also reported that miR-663 acted as a tumor suppressor in glioblastoma by targeting CXCR4 and PIK3CD." (PMID 27667893, 2016). "Along those lines, the chemokine SDF-1 (stromal cell-derived factor-1, CXCL12) via its receptor CXCR4 stimulates migration of glioblastoma cells." (PMID 26893360, 2016). "The CXCL12/CXCR4 pathway regulates tumor cell proliferation, metastasis, angiogenesis and the tumor-microenvironment cross-talk in several solid tumors, including glioblastoma (GBM), the most common and fatal brain cancer." (PMID 27015814, 2016). "The effects of peptide R on CXCR4 expression, cell survival and migration were assessed on the human glioblastoma cell line U87MG exposed to CXCL12, by immunofluorescence and western blotting, MTT assay, flow cytometry and transwell chamber migration assay." (PMID 27015814, 2016). "The human glioblastoma U87MG cell line was used for the evaluation of CXCR4 expression, cell proliferation and migration in in vitro assays, as well as for intracranial xenografts in nude mice for in vivo studies." (PMID 27015814, 2016). "Different types of cyto-chemokines are involved in the crosstalk between hAT-MSCs and BTICs (medulloblastoma and AT/RT: CXCR4/SDF-1, CCR5/RANTES, IL6R/IL-6 and IL8R/IL8; glioblastoma: CXCR4/SDF-1, IL6R/IL-6, IL8R/IL-8 and IGF1R/IGF-1)." (PMID 26076490, 2015). "Synergistic inhibition of migration of hAT-MSCs toward glioblastoma-BTICs was also confirmed after double knock down of CXCR4 + IGF1R." (PMID 26076490, 2015). "It has been recently reported that a CXCR4 antagonist prevented the influx of monocytes and inhibited tumor growth, resulting in abrogation of glioblastoma recurrence after irradiation in mice." (PMID 25478952, 2014). "Specifically, they observed that the interaction between PDGFR and CXCR4 is essential in glioblastoma cell chemotaxis." (PMID 24651576, 2014).
glioblastoma (continued). "We provide evidence of co-expression of CXCR4 and PDGFRβ in a human glioma cell line and in several primary glioblastoma specimen from patients." (PMID 24023874, 2013). "In this paper we demonstrated a functional cross talk between two receptors largely expressed in glioblastomas and playing key roles in tumor cell proliferation, infiltration and angiogenesis, PDGFRβ and CXCR4." (PMID 24023874, 2013). "Our data suggest that CXCR4 modulates the progress of glioblastoma by maintaining the properties of GSCs." (PMID 23961808, 2013). "Collectively, our results indicate that CXCR4 and CXCR7 are involved in important activities associated with glioblastoma progression." (PMID 23555768, 2013). "In accordance with previous studies, we demonstrated that the CXCL12/CXCR4 axis plays a substantial role in regulating the proliferation, drug resistance, and neovascularization of glioblastoma." (PMID 23961808, 2013). "CXCR4 is known to be involved in the proliferation and angiogenesis of glioblastoma and in determining its invasiveness and resistance to drugs." (PMID 23961808, 2013). "Among them, the chemokine CXCL12/SDF-1 appeared of interest as its receptors CXCR4 are widely expressed in glioblastoma tissue, and their activation plays a key role in the migration of glioblastoma cells." (PMID 22675627, 2012). "This review discusses the roles of the chemokine stromal cell-derived factor-1 and its receptor CXC chemokine receptor 4 (CXCR4) in affecting the sensitivity of glioblastomas to irradiation." (PMID 21587260, 2011). "Introduction of LRRC4 into glioblastoma cells reduced CXCR4 expression, CXCL12-induced ERK and AKT phosphorylation and matrix metalloproteinase expression." (PMID 20376365, 2010). "CPZ1344 activity against the CXCR4/CXCL12 axis was investigated on glioblastoma cells." (PMID 40142155, 2025). "In addition, the presence of VEGF and HIF-1 stimulates the expression of CXCR4 in human brain microvascular endothelial cells, and this event promotes angiogenesis in human glioblastoma." (PMID 40142155, 2025). "Inhibition of CXCR4 reduces tumor invasion in glioblastoma cells and increases their sensitivity to radiotherapeutic agents while suppression of β1-integrin could favor cells not to settle around pre-existing blood vessels." (PMID 38255995, 2024). "Additionally, priming MSCs with the cytokine TGF-β has been shown to increase their CXCR4-driven homing to glioblastoma, while MSCs stimulated with IL-1β showed an upregulated CXCR4 expression, increased production of metalloproteinases and enhanced migration." (PMID 39062449, 2024). "CXCR4 imaging for glioblastoma can be particularly valuable in several ways: (i) Identifying patients whose tumors express CXCR4 could aid in stratifying treatment approaches, potentially guiding the use of CXCR4-targeted therapies." (PMID 39162901, 2024). "In addition to demonstrating the efficient synergistic action of the two compounds, these in vitro data confirmed the blockade of the CXCR4/MDM2/4 axis as a valid strategy to reduce glioblastoma proliferation." (PMID 36980182, 2023). "Moreover, it was demonstrated that the CXCL12/CXCR4 pathway is overexpressed in histopathological specimens of human glioblastoma." (PMID 36980182, 2023). "Additionally, glioblastoma stem cells have been found to express the receptor C-X-C receptor type 4 (CXCR4), which interacts with the chemoattractant stromal-derived factor-1α (SDF-1α)." (PMID 37560473, 2023). "A nanocarrier conjugated lipophilic thiobenzoate complex of rhenium-188 loaded in the core of a lipid nanocapsule, containing a CXCR4 function-blocking antibody named 12G5 (12G5-LNC188Re), was investigated by Séhédic and colleagues in an in vivo model of glioblastoma." (PMID 36980182, 2023). "Therefore, since the overactivation of the chemokine receptor CXCR4 is extremely harmful in glioblastoma, drug designers have developed targeted pharmacological agents." (PMID 36980182, 2023).